DKK1 (dickkopf Wnt signaling pathway inhibitor 1)
Diseases named in the same sentence as DKK1 in open-access papers (continued):
Sharing a sentence is not in itself a finding about the gene and the disease.
breast carcinoma (continued). "DKK1 expression has been investigated in various cancers; DKK1 is overexpressed in multiple myeloma and breast cancer but weakly expressed in colon and cervical cancers." (PMID 35625973, 2022). "Dkk1 is a secreted protein that suppresses tumor metastasis and is also an inhibitor of Wnt signaling, which has been shown to promote breast cancer progression." (PMID 36052258, 2022). "Consistent with elevated DKK1 levels in lymph node metastases in breast cancer, 231 LM and 4T1 LM cells exhibited elevated DKK1 levels compared to their respective parental cells." (PMID 35296660, 2022). "An example can be seen in breast cancer bone invasion, whereby miR-301a-d regulates DKK-1, RUNX-2 and ITGA5 genes, which are involved in osteogenesis, leading to breast cancer osteomimicry." (PMID 34680611, 2021). "Recently, ursolic acid has been shown to decrease the β-catenin levels by increasing the level of Wnt antagonists, sFRP4 and DKK1, in breast cancer stem-like cells." (PMID 34584036, 2021). "In breast cancer cells, DKK1 inhibits migration and invasion though suppression of the β-catenin/MMP7 pathway." (PMID 33613114, 2021). "In breast cancer, tumor-secreted DKK1 suppressed lung metastasis by downregulating PTGS2-induced macrophage and neutrophil recruitment by antagonizing non-canonical SOX2 and SOX9 signaling." (PMID 34093545, 2021). "Elevated DKK1 expression in multiple myeloma and prostate cancer leads to enhanced bone metastasis, and the expression level of DKK1 affects the organotropism of breast cancer metastasis." (PMID 35008201, 2021). "For instance, PRMT5 aids cellular proliferation, migration, and invasion in breast cancer cells by inhibiting the expression of Dickkopf WNT signaling pathway inhibitor 1 (DKK1) and DKK3, known antagonists of the wnt/β-catenin pathway." (PMID 34685445, 2021). "According to other findings, DKK1 overexpression was also observed in breast cancer, ovarian serous carcinoma, lung and esophageal carcinoma." (PMID 34093545, 2021). "Dkk-1 was highly expressed in breast cancer patients who predominantly developed osteolytic bone metastases." (PMID 34437475, 2021). "It was previously reported that B cell‐specific Moloney mouse leukemia virus integration site 1 (Bmi1) activates the Wnt pathway by inhibiting the expression of DKK1 in breast cancer cell lines and 293T cells." (PMID 33639034, 2021). "While according to this study an inhibition of DKK1 would be beneficial, in other studies, including breast cancer, a tumor-suppressive effect of DKK1 with respect to migration and invasion was observed." (PMID 34638464, 2021). "Before our study, LNCAROD was demonstrated to activate DKK1 transcription in breast cancer MCF‐7 cell." (PMID 32216017, 2020). "Additional Wnt family regulators are also highly expressed within bone metastasis including the Wnt-antagonist Dickopf-1 (DKK1), which has increased expression in breast cancer metastasis and promotes apoptosis of osteoblasts." (PMID 32751181, 2020). "Dkk-1, a Wnt inhibitor, had been identified as a serological marker of breast cancer metastatic organotropism and inhibits lung metastasis." (PMID 33384994, 2020). "DKK1 is upregulated within bone metastases of breast cancer as well as within serum from patients with bone metastasis." (PMID 32751181, 2020). "DKK1 inhibits migration and invasion of breast cancer cell through suppression of β-catenin/MMP7 pathway, our findings offered a potential alternative for breast cancer prevention and treatment." (PMID 31285694, 2019). "A detailed analysis of the molecular mechanisms underlying bone metastasis revealed that in the osteoblasts of breast cancer patients with a high DKK1 expression, suppression of the canonical Wnt signaling pathway reduced osteogenesis." (PMID 31698687, 2019). "Other recent studies showed that DKK1 is a serological marker of breast cancer metastasis organotropism, suppressing lung metastasis but promoting bone metastasis of breast cancer." (PMID 31568519, 2019).
breast carcinoma (continued). "DKK1 expression is a predictive biomarker of metastasis in the surgical specimens of breast cancer patients." (PMID 31698687, 2019). "MDA-MB-231_BH; DKK1 p < 0.0001, Vantictumab p < 0.0001), and in early breast cancer samples (DKK1; p = 0.0222, Vantictumab; p = 0.0060) (n = 10)." (PMID 31676788, 2019). "Here, we demonstrate MMP7 is an important target downstream of DKK1 in breast cancer cells, based on the following studies: knockdown of DKK1 is associated with enhanced level of MMP7 in MDA-MB-231 and MCF-7 cells." (PMID 31285694, 2019). "In this study, our results showed DKK1 overexpression resulted in decreased cell migration and invasion in breast cancer cells." (PMID 31285694, 2019). "DKK1 suppressed breast cancer cell migration and invasion through suppression of β-catenin and MMP7 expression." (PMID 31285694, 2019). "DKK1 suppressed breast cancer cell migration and invasion by alleviating β-catenin/MMP7, our findings offered a potential alternative for breast cancer prevention and treatment." (PMID 31285694, 2019). "It was previously reported that PTOV1 cloud impaired the expression of DKK1, a negative regulator of β-catenin, to activate β-catenin signaling in breast cancer." (PMID 31387622, 2019). "A retrospective analysis of 102 breast cancer patients revealed that the DKK1 expression in breast cancer was significantly higher in patients with bone metastasis." (PMID 31698687, 2019). "In the present study, we found introduction of DKK1 into breast cancer cells inhibited β-catenin protein expression in breast cancer cells, while knockdown of DKK1 promote β-catenin expression." (PMID 31285694, 2019). "Taken together, these results showed that DKK1 inhibits breast cancer migration and invasion through suppression of β-catenin/MMP7 signaling pathway." (PMID 31285694, 2019). "The authors showed that the suppression of DKK-1 by statin and amino-bisphosphonates inhibited the ability of breast cancer cells to block WNT3A-induced production of alkaline phosphates and bone-protective osteoprotegerin in preosteoblastic C2C12 cells." (PMID 30420710, 2018). "In our group of patients on AIs therapy, serum levels of DKK1 were measured after the surgical removal of the breast cancer and during AIs adjuvant treatment, while in the control group of patients they were measured prior to the treatment." (PMID 30227689, 2018). "DKK1 inhibited breast cancer metastasis to lungs together with reduced macrophage and neutrophil infiltration, and impaired TGF-β expression." (PMID 30597969, 2018). "DKK1 methylation has been reported in 27% of breast cancer cell lines and 19% of breast cancer patients." (PMID 28029646, 2017). "It has also been suggested that breast cancer cells with over-activated Wnt/β-catenin signaling produce high levels of DKK1, which is involved in breast cancer-derived osteolytic metastases." (PMID 29108326, 2017). "DKK1 was proposed as an independent prognostic biomarker of relapse-free survival in patients with breast cancer." (PMID 28178355, 2017). "A recent study showed that CBX7 recruited p300 acetyltransferase to the DKK1 promoter region, driving DKK1 expression in breast cancer cells and leading to the impairment of Wnt/β-catenin signaling and breast tumorigenesis." (PMID 28030829, 2017). "Increased serum level of DKK1, an inhibitor of the Wnt-β-catenin pathway, has been reported in pancreatic, gastric, hepatic, lung, esophagus, and breast cancer patient." (PMID 28178355, 2017). "We observed that basal DKK1 levels of the age-matched healthy women were significantly lower than those of breast cancer survivors (healthy women vs. breast cancer survivors, 1831 ± 161 vs. 2594 ± 128 pg/ml, p < 0.001)." (PMID 28178355, 2017). "A previous study demonstrated that the serum level of DKK1 in breast cancer was correlated with tumor grade and lymph node metastasis." (PMID 28178355, 2017).
breast carcinoma (continued). "Paradoxically, DKK1 levels were found to be markedly increased in patients with breast cancer compared with both, women in complete remission and healthy controls." (PMID 28178355, 2017). "Spearman’s rank order correlation coefficients of relative gene expression values for SOX2, AXIN2, and DKK1 in breast cancer samples from The Cancer Genome Atlas (TCGA_BRCA_exp_HiSeqV2-2015-02-24) data set (n = 1,009), *p < 0.05." (PMID 28929082, 2017). "Overexpression of DKK1 has also been reported in many cancers, including breast cancer, prostate cancer, lung cancer, and multiple myeloma." (PMID 28929082, 2017). "Dickkopf-1 (DKK-1) is preferentially expressed in tumors with poor prognosis, ER− breast cancer and endocrine therapy-resistant tumors." (PMID 28929082, 2017). "Higher serum levels of DKK1 were correlated with bone metastasis of breast cancer and its mortality." (PMID 28178355, 2017). "NMI is also reported to inhibit tumor growth through up-regulating Dkk1, and loss of NMI promotes EMT by activation of TGFβ/SMAD signaling in breast cancer." (PMID 28077802, 2017). "In line with our results, silencing of BMI-1 in breast cancer cells was shown to impair Wnt signalling via downregulation of Wnt ligands (e.g. Wnt3a) and upregulation of Wnt inhibitors including DKK1." (PMID 26935956, 2016). "An aberrant splicing of LRP5, which removes the coding region of LRP5 that interacts with the extracellular antagonist DKK1, has been reported in human breast cancer." (PMID 27420097, 2016). "Some reports discovered that DKK1 was overexpressed in multiple myeloma, hepatoblastomas, Wilms' tumors, breast cancer and hepatocellular carcinoma (HCC), and functioned as a tumor promoter." (PMID 26799283, 2016). "Numerous studies have demonstrated that DKK1 is involved in tumorigenesis in many types of cancer, including breast cancer, lung cancer, esophageal carcinomas, HCC and malignant bone disease." (PMID 27608843, 2016). "Breast cancer cells make sclerostin and DKK1, whereas serum DKK1 is increased in patients and contributes to osteolytic bone destruction in breast cancer bone metastases." (PMID 25757219, 2014). "The DKK-1 levels in serum from patients with breast cancer (n = 125), and from healthy individuals (n = 53) were detected by ELISA." (PMID 25116444, 2014). "Suppression of DKK-1 inhibited the ability of breast cancer cells to block WNT3A-induced production of alkaline phosphates and bone-protective osteoprotegerin in preosteoblastic C2C12 cells." (PMID 24528599, 2014). "Clinical relevance was validated by analyzing DKK-1 expression in the tissue and serum of women with breast cancer exposed to bisphosphonates." (PMID 24528599, 2014). "Immunohistochemical staining of primary breast cancer tissue revealed a medium to strong expression of DKK-1 in 70% (52/74) of evaluated breast cancer cases, mainly in the cytoplasm." (PMID 24528599, 2014). "Regulation of DKK-1 by bisphosphonates and statins was assessed in human breast cancer cell lines, and the role of the mevalonate pathway and downstream targets was analyzed." (PMID 24528599, 2014). "Larger clinical trials are therefore needed to fully define the prognostic value and pathophysiological role of DKK-1 in breast cancer." (PMID 24528599, 2014). "Thirdly, univariate and multivariate analyses showed that the serum DKK-1 level was independent prognostic parameter of overall survival and relapse-free survival in breast cancer patients." (PMID 25116444, 2014). "Secondly, Kaplan–Meier analysis showed that breast cancer patients with high serum DKK-1 expression level had distinctly shorter overall survival and relapse-free survival." (PMID 25116444, 2014). "In contrast to myeloma bone disease, the role of DKK-1 in breast cancer and prostate cancer is less clear." (PMID 24528599, 2014). "We assessed the effects of mevalonate pathway inhibition on DKK-1 expression in osteotropic breast cancer." (PMID 24528599, 2014).
breast carcinoma (continued). "In spite of these studies, there little has been reported on the significance of DKK-1 expression in breast cancer progression and prognosis." (PMID 25116444, 2014). "When co-incubated with supernatants from different breast cancer cell lines, those with high baseline levels of DKK-1 inhibited ALP induction by WNT3A, whereas MCF-7 and T47D cells with low DKK-1 levels had a smaller effect." (PMID 24528599, 2014). "DKK-1 is a novel target of the mevalonate pathway that is suppressed by zoledronic acid and atorvastatin in breast cancer." (PMID 24528599, 2014). "In our study, inhibition of the mevalonate pathway resulted in a profound suppression of DKK-1 in vitro and in breast cancer patients receiving zoledronic acid." (PMID 24528599, 2014). "DKK1 is frequently upregulated in human breast cancer tissue and in metastatic cancer cells and is involved in development and progression of osteolytic metastasis." (PMID 25147739, 2014). "In line with the in vitro data, treatment of breast cancer patients with zoledronic acid decreased DKK-1 levels by a mean of 60% after 12 months of treatment." (PMID 24528599, 2014). "Elevated DKK-1 levels are described in breast cancer patients with confirmed bone lesions and a recent study defined high levels of DKK-1 as a negative prognostic marker in triple-negative breast cancer." (PMID 24528599, 2014). "The mean serum level of DKK-1 in patients with breast cancer was 4.99 ± 1.50 ng/mL, and was significantly higher than that in healthy individuals (1.88 ± 0.81 ng/mL, P < 0.001)." (PMID 25116444, 2014). "Regulation of DKK-1 was strongest in osteolytic breast cancer cell lines with abundant DKK-1 expression." (PMID 24528599, 2014). "The relationships between serum DKK-1 levels and clinicopathological characteristics of patients with breast cancer were analyzed." (PMID 25116444, 2014). "The DKK-1 expression level was classified as high or low in relation to the median value, and patients with breast cancer (n = 125) were divided into a high expression group (n = 63) and a low expression group (n = 62)." (PMID 25116444, 2014). "While healthy controls had mean DKK-1 serum levels of 23.8 pmol/l (n = 27), these levels significantly increased to 33.4 pmol/l (n = 28) in breast cancer patients (P = 0.006; 95% confidence interval = -16.32 to -2.876)." (PMID 24528599, 2014). "In the present study we investigated the expression of DKK-1 in patients’ serum to establish if DKK-1 can be used as a novel prognostic biomarker in human breast cancer." (PMID 25116444, 2014). "In metastatic breast cancer, serum levels of DKK-1 are increased, and breast cancer-derived DKK-1 has the ability to inhibit osteoblast differentiation." (PMID 24528599, 2014). "All the results suggested that serum DKK-1 level was befitting to predict prognosis of breast cancer patients after surgery." (PMID 25116444, 2014). "Down regulation of the inhibitor Dickkopf 1 (DKK1) in a lung metastases derived MCF7-LM cell line demonstrates the importance of Wnt regulation in the metastatic process in breast cancer." (PMID 23861811, 2013). "Further studies are required to examine the importance of DKK-1 as a therapeutic target for breast cancer bone metastasis." (PMID 26237142, 2013). "In this study we reported that DKK1 protein was expressed in breast cancer hormone-resistant cell lines MDA-MB-231, MDA-MB-231-HM and MDA-MB-435." (PMID 22649545, 2012). "The levels of DKK1 mRNA in 6 different breast carcinoma cell lines were compared with those in the normal MCF10A breast cell line and in Hela cell line." (PMID 22649545, 2012). "Next we investigated the relationship between DKK1 and beta-catenin expression level in clinical breast cancer samples by immunohistochemical staining." (PMID 22649545, 2012). "Breast cancer cells secrete Dickkopf-related protein 1(DKK1), an antagonist of the Wnt/β-catenin pathway that blocks osteoblast differentiation." (PMID 22032690, 2011).
breast carcinoma (continued). "To test this prediction, we treated MCF-7 breast cancer cells by graded doses of Dkk1 applied at schedules detailed in Materials and Methods." (PMID 21915302, 2011). "It has recently been shown that metastatic breast cancer cells secrete DKK1 and that it contributes to their ability to inhibit osteoblast differentiation in vitro." (PMID 22032690, 2011). "Overexpression of DKK1 in a breast cancer cell line resulted in an inhibition of self-renewal ability." (PMID 21952072, 2011). "It is, therefore, likely that both sclerostin and DKK1 cooperate to inhibit Wnt signaling in osteolytic lesions in breast cancer bone metastases." (PMID 22032690, 2011). "The model suggested that the Wnt pathway inhibitor, Dickhopf1 (Dkk1), was the QS molecule in breast cancer, and that high levels of this protein will drive BCSCs into differentiation, leading to tumor elimination." (PMID 20406437, 2010). "We have been able to identify important node genes in the BANs, namely DKK1 in colon cancer cells, UGT1As in breast cancer cells and EEF1A1 in pancreatic cancer, leukemia and osteosarcoma cells." (PMID 19732436, 2009). "Our finding of epigenetic silencing of SFRP genes and DKK1 in breast cancer cell lines prompted us to determine the extent to which these Wnt antagonist genes are also aberrantly methylated in primary breast tumours." (PMID 18283316, 2008). "In contrast to SFRP genes, however, the frequency of DKK1 methylation in breast cancer was relatively limited." (PMID 18283316, 2008). "In summary, our data show that Dkk-1 is produced by human osteolytic breast cancer cells and higher circulating levels were found in women with breast cancer and bone metastases." (PMID 17876334, 2007). "Altogether, cluster analysis revealed significant preferential DKK1 expression in familial and hormone-resistant breast cancers, which also encompassed the most aggressive tumours." (PMID 17245340, 2007). "We found lower but detectable levels of Dkk-1 in women with breast cancer in complete remission and in healthy women." (PMID 17876334, 2007). "Further studies are required to delineate the role of Dkk-1 in the physiopathological mechanisms of breast cancer-induced bone metastases." (PMID 17876334, 2007). "The relevance of our preclinical findings in humans is suggested by the increased levels of Dkk-1 in the serum of patients with breast cancer and bone metastases measured by a new sensitive and reproducible assay that we developed." (PMID 17876334, 2007). "Among the different genes listed, we confirmed that DKK1 was expressed in breast cancer cells, with restricted expression in the placenta." (PMID 17245340, 2007). "We also evaluated expression depending on familial history, and 48% of DKK1+ tumours arose from women reporting familial cases of breast cancer." (PMID 17245340, 2007). "Altogether, these data demonstrate DKK1 production (mRNA and protein) from breast cancer specimens, with a preferential expression pattern in tumours with poor outcomes." (PMID 17245340, 2007). "We first analysed Dkk-1 expression by human breast cancer cell lines that induce osteolytic or osteoblastic lesions in animals." (PMID 17876334, 2007). "There was a significant difference in serum Dkk-1 levels between the different groups of patients with breast cancer and healthy controls by ANOVA (P=0.0002)." (PMID 17876334, 2007). "When we compared the cohort tested, DKK1 expression was preferentially and significantly expressed in women with familial cases of breast cancer (P=0.024)." (PMID 17245340, 2007). "The secretion of Dkk-1 was assessed by ELISA of the culture supernatant of human breast cancer cell lines." (PMID 17876334, 2007). "To further characterise DKK1 expression in breast cancer tumours, we next assessed DKK1 expression profiles in clinical breast cancer specimens." (PMID 17245340, 2007).